CCL21 (C-C motif chemokine ligand 21)
Diseases named in the same sentence as CCL21 in open-access papers (continued):
Sharing a sentence is not in itself a finding about the gene and the disease.
tumor (continued). "The interaction of LEC-derived chemokine CCL21 with tumor CCR7 receptors promotes the formation of tumor–lymphatic interfaces that contribute to metastasis." (PMID 38201272, 2023). "The differences in Il-10 and Il-1β expression changes between recombinant CCL21 treatment and upon CCL21 neutralization from GBM CM suggests that CCL21 cooperates with other soluble factors secreted by tumor cells to induce TAM polarization in the TME." (PMID 37314567, 2023). "The ability of CCL21 to stimulate T cell and DC migration suggests that CCL21 plays a key role in an effective immune response in the tumor microenvironment." (PMID 37664721, 2023). "These persistent changes in the microenvironment and their influence on inflammatory infiltrates including CCL21 with regard to lymphatic function and promotion of tumor growth warrant further study." (PMID 37801190, 2023). "Mechanistically, CCL21 induced Erk1/2 and Akt phosphorylation in tumor cells and CCR7 knockdown abrogated Akt and Erk1/2 activation." (PMID 37314567, 2023). "An improved method of delivery to the tumor of the modified S. typhimurium expressing mouse CCL21, avoiding systemic distribution, was reported by Din and collaborators." (PMID 37185750, 2023). "Manipulation of S. typhi to express either the proapoptotic Fas ligand or CCL21(chemokine with anti- tumor properties) as a delivery vehicle carrying anti- cancer therapeutics has demonstrated primary tumor inhibition." (PMID 38090593, 2023). "The cell cluster (TEC_CCL21) interacts with almost all immune cells, and CCL21 has been shown to promote tumor immune escape." (PMID 37914817, 2023). "In combination with CCL21, IL-7 improved the anti-tumor activity of CLDN18.2-specific CAR T-cells in a syngeneic mouse model without lymphodepletion." (PMID 38201551, 2023). "CCL21 was also reported to be expressed in mouse GL261 tumor and stromal cells in vivo, and correlated to macrophage recruitment and tumor cell survival." (PMID 37314567, 2023). "Growing evidence suggests that the interaction between CCL21 and CCR7 in the tumor microenvironment is associated with poor prognosis in various types of human cancer." (PMID 37664721, 2023). "We show that tumor cell intrinsic and extrinsic processes are involved in CCL21 dependent enhancement of the TMZ response." (PMID 37314567, 2023). "GBM CM-treated microglial cells showed similar increased expression of tumor-supporting proteins such as Arg1, that was abrogated by CCL21-blocking Abs." (PMID 37314567, 2023). "The chemokine CCL21 was adenovirally engineered to be secreted from an anti-tumor DC vaccine to elicit signaling through CCR7 expressed on endogenous dendritic and T cells." (PMID 36167831, 2023). "As the DC vaccine is injected intratumorally, this establishes a gradient of CCL21 that promotes infiltration of those endogenous cells into the tumor, which has been shown to increase synergistic anti-tumor effects between adoptive and endogenous cells." (PMID 36167831, 2023). "ELISA analysis of macrophage culture supernatants provided convergent data, showing that GBM tumor cells treated with shCCL21 siRNA to knockdown Ccl21 produced less VEGF-A and IL-10 than shCTRL-transduced GBM cells." (PMID 37314567, 2023). "The addition of CCL19 and CCL21 increased the infiltration of endogenous dendritic cells, while CCL21 also showed inhibition of tumor angiogenesis." (PMID 38201551, 2023). "In a phase I trial (NCT01574222), patients with lung cancer who received injections of CCL21‐modified DCs exhibited tumour‐specific immune responses." (PMID 36808888, 2023). "In multiple murine tumor models, intratumoral injection of CCL19 or CCL21 increases the numbers of tumor-infiltrating DCs and T cells, retards tumor growth, and prolongs the survival of tumor-bearing mice." (PMID 38008741, 2023). "For optimal therapeutic use of CCL21, the contribution of host-derived CCL21-Ser to tumor growth and its role in vivo must be fully understood." (PMID 37664721, 2023).
tumor (continued). "With respect to the gene expression profile, CCL21 increased the expression of tumor-supportive genes such as Vegfa, Mrc1, Arg1, and Cd274 (PD-L1) in microglia, as well as in BMDMs that also showed increased expression of Il-10 and Tgfβ1." (PMID 37314567, 2023). "A significant number of studies have demonstrated that systemic or local CCL21 expression promotes anti-tumor response by recruiting lymphocytes and DCs into tumor tissue." (PMID 37664721, 2023). "Other tumor angiogenesis-related chemokines and their receptors, such as CCL21/CCR7 and CXCL4, can be used as targets for anti-tumor angiogenesis therapy." (PMID 35770088, 2022). "It has been demonstrated that CCL21/CCR7 signalling axis plays a crucial role in the lymphatic metastasis of many tumours." (PMID 35280672, 2022). "This study aimed to produce epitopes of CCL21 and IL1β as a recombinant protein and characterize its in vitro anti-tumor and immunogenic activity." (PMID 36037155, 2022). "The enhanced lymphatic flow resulting from tumour-induced lymphangiogenesis upregulates CCL21 expression on LECs." (PMID 35072206, 2022). "CCL21 gradients attract DCs from the tumor intertitium to the lymphatic vasculature upon binding to the receptor CCR7." (PMID 35269922, 2022). "VEGFC accumulated in the tumor context induces tumor lymphatic vessels to release chemokines such as CCL19 and CCL21 that can attract tumor cells through their binding to CCR7." (PMID 36612017, 2022). "CCR7-siRNA can inhibit the migration of tumour cells by reducing CCL21/CCR7 binding by inhibiting CCR7 expression at mRNA level." (PMID 35280672, 2022). "Treated mice showed increased infiltration of DCs as well as an inhibition of the tumor angiogenesis (presumed effect of CCL21)." (PMID 35211124, 2022). "Meanwhile, researchers found that the increased expression of CCL19 and CCL21 in tumors can result in infiltration of TILs and an improved prognosis for many tumor patients." (PMID 35065633, 2022). "With this initial test, thus, it was possible to determine the role of CCL21/IL1β in migration and movement of immune cells towards tumor cells." (PMID 36037155, 2022). "For example, CCR7 and its ligands (CCL19/CCL21) are a vital axis for carcinogenic properties, such as epithelial-mesenchymal transition, tumor invasion and migration." (PMID 36291815, 2022). "As tumor PD-L1 expression was also upregulated, it is conceivable that Ad-CCL21-DC reverses ICI resistance and will be synergistic with ICI therapy." (PMID 35806328, 2022). "Based on the transcriptome and fecal microbiota data, the increased abundance of Clostridium XIVa accompanied by a decrease in CCL21, which facilitates tumor growth, indicates an unfavorable prognosis." (PMID 36583106, 2022). "Interstitial pressure promotes the production of CCL21 cytokines in the tumor microenvironment, and high levels of CCL21 can alter the form of antigen presentation and inhibit the movement of immune cells to the tumor." (PMID 35402878, 2022). "Tumours associated with hypoxia are immunosuppressive and lack high expression of CCL21 and therefore therapeutic use of recombinant chemokines (such as CCL21) to stimulate immune cell recognition in tumours is being considered as a novel treatment approach." (PMID 35355992, 2022). "For LTi cells, their recruitment to the tumor site is related to CCL21 expression by tumor cells, indicating immune tolerance and invasion." (PMID 35646915, 2022). "In the tumor microenvironment, CCL21 acts as a potent chemoattractant for CCR7-positive tumor cells by binding to podoplanin on cancer-associated fibroblasts (CAFs), thereby promoting the stromal invasion of cancer cells." (PMID 35163233, 2022). "In turn, downregulating the expression of CCR7 or blocking the CCL21/CCR7 axis ultimately led to the decrease in migration of tumour cells after PTX chemotherapy." (PMID 35280672, 2022).
tumor (continued). "The study reported PDPN overexpression due to hypoxia in fact favoured invasion of CCR7+ tumour cell into CCL21+ peripheral lymph nodes leading to metastasis." (PMID 35355992, 2022). "At the molecular level, CCL21/CCR7 can promote lymphatic metastasis of tumours via activating the ERK1/2 22 and JAK2/STAT3 signalling pathways." (PMID 35280672, 2022). "Several studies have revealed that CCL19 and CCL21 can vigorously drive the chemotaxis migration of CCR7-expressing tumor cells." (PMID 35874608, 2022). "As another example, DC trafficking from the tumor to the draining lymph node is driven by the secretion of CCL21 by lymphatic endothelial cells, which creates a gradient in the perilymphatic interstitium." (PMID 35269922, 2022). "Mechanistically, VEGF-C-driven modulation of RT-triggered anti-tumor immunity was attributed to C-C Motif Chemokine Ligand 21 (CCL21)-dependent DC trafficking and CD8+ T cell activation." (PMID 35301438, 2022). "Taken together, these observations indicate that CCL19 and CCL21 inhibit the growth of HCC by enhancing the infiltration of tumor-infiltrating T cells and B cells." (PMID 35673582, 2022). "Blocking the CCL21/CCR7 axis signalling pathway significantly inhibits the migration of tumour cells treated with PTX." (PMID 35280672, 2022). "CCL21 has been previously shown to be downregulated in EGFR-driven tumours and contribute to an immunosuppressive TME, which can be confirmed by our data." (PMID 36010935, 2022). "The TLS-related molecule CXCL13 is associated with good prognosis in HCC patients, and the expression of CCL19 and CCL21 in tumours can promote the anti-tumour effect of TILs." (PMID 36291944, 2022). "Identifying the sources of chemokines, CCL8 and CCL21 is critical for both targeting cancer cells and particularly modifying stromal and immune cells via tumor inhibitory mechanisms." (PMID 34160019, 2021). "During tumor metastasis through the initial lymphatics, lymphatic endothelial cells were known to secrete CCL21 and attracted cancer cells expressing CCR7 and CCL21 receptors." (PMID 34671596, 2021). "Approximately one-third of cDC1 in tumor tissues express high levels of CCR7 (a receptor of CCL21, which is produced by lymphatic endothelial cells and LN stromal cells)." (PMID 34572844, 2021). "Recently tenascin-C was shown to contribute to the immune-suppressive microenvironment of the tumor stroma through integrin α9β1 inducing CCL21 (in lymphatic endothelial cells) and TLR4 regulating CCR7 (in CD11c+/dendritic cells)." (PMID 33912190, 2021). "In the macrofluidic device, the CCL21 level in the lymphatic endothelial cells was facilitated by coculture with noninvasive tumor spheroids (BT474 and A549) under the synergic stimuli." (PMID 34671596, 2021). "The tactic is to retain the inhibitory effect of chemotaxis from CCL21 while block other tumour-promoting effects sufficiently." (PMID 34060588, 2021). "It has been reported that CCL1, CCL2 and CCL21 affect tumor metastasis and progression through direct or indirect interactions with lymph nodes." (PMID 34321012, 2021). "In HEVhigh tumours compared with HEVlow tumours, gene profile of HEVs has shown upregulation of genes encoding lymphoid chemokines including chemokine (C-C motif) ligand (CCL) 19 (CCL19), CCL21, and CXCL13 as well as T-cell homing receptors (CCR7 and LSEL)." (PMID 33917287, 2021). "Some studies showed that microenvironmental factors of the tumor increase the CCL21 expression level in the lymphatic endothelial cells, and induced a tumor invasion." (PMID 34671596, 2021). "In subsequent preclinical studies, we found that intratumoral administration of dendritic cells overexpressing CCL21 generates systemic antitumor responses and confers tumor immunity." (PMID 34806054, 2021). "TRCs and PRCs exhibited similar expression levels for CCL21, but it appeared that both subsets lost proportions of CCL21+ cells during tumor conditions." (PMID 34706240, 2021).
tumor (continued). "CCL21 plays a role not only in immunity, but also in regulating the biological processes of tumor cells." (PMID 34321013, 2021). "For instance, CXCL10, CXCL12, CCL1, CCL19 and CCL21 produced by LECs can be sensed by tumor cells expressing cognate receptors and stimulate their chemoattraction towards lymphatic vessels." (PMID 33808959, 2021). "For instance, LIGHT-VTP in mouse PNET increases the expression of Ccl21 in the vascular bed and in CD68+ tumor-resident macrophages associated with TLS." (PMID 34122434, 2021). "In CC10-TAg mice, intrapulmonary administration of engineered CCL21-expressing DC also induced tumor T cell infiltration and specific anti-tumor responses in spontaneous broncho-alveolar carcinoma, thus decreasing tumor burden." (PMID 34276690, 2021). "CCL21 promotes immune activity in the tumor microenvironment (TME) by colocalizing dendritic cells (DC) and T cells programming ectopic lymph node architectural structures that correlate with cancer prognosis." (PMID 34321013, 2021). "Identifying the sources of the CCL8 and CCL21 in the tumor microenvironment and developing targeting strategies for these chemokines to prevent tumor growth will improve both prognosis and therapeutic outcomes." (PMID 34160019, 2021). "The results showed that KIAA1429, HAMP, AQP9, CCL13, and CCL21 were significantly negatively correlated with tumor purity, and KIAA1429 was highly correlated with B cells, CD8 T cells, CD4 T cells, macrophages, neutrophils, and dendritic cells." (PMID 34422053, 2021). "Comparing tumor to tumor in scenario 2, Ccl21 and Klf7 were normalized by SPI ingestion, relative to basal diet." (PMID 34494932, 2021). "Increases expression of CCL21.Orchestrates an immune-suppressive microenvironment to facilitate tumor escape from immunosurveillance." (PMID 33790909, 2021). "As such, CCL21 and IL-21 are potent activators of the immune system when used together for tumor therapy." (PMID 33802281, 2021). "Different chemokines, such as CCL5 and CCL19, have been expressed in various types of virus; in particular, CCL20 and CCL21 have shown to enhance anti-tumor effects when used to arm Onc.Ads." (PMID 33802281, 2021). "A significant tumor growth suppression was also observed with the CCL21 nanovaults in the preclinical trials." (PMID 34138386, 2021). "An increase of CCL21 in the tumor tissue will potentially impede DC migration, mediated by the CCL21 chemokine gradient between the tumor tissue and the tumor-draining lymph nodes (TdLNs)." (PMID 34638505, 2021). "The expression of CCL21 and endothelium proteins such as peripheral node addressin in LN-like vasculature found within solid tumors helps with anti-tumor T cell infiltration and positive prognosis in murine models." (PMID 33841445, 2021). "After internalizing the tumor antigens, these cDC subsets transmigrate into the lymphatic vessels via CCL21, CXCL12, and CX3CL1." (PMID 34572844, 2021). "The anti-PD-1, CCL21-DC tumor lysate vaccine, and anti-PD-1 plus CCL21-DC tumor lysate vaccine treatments resulted in 3-, 3-, and 19-fold weight changes of tumors at the end of therapy in comparison to control, respectively." (PMID 32570793, 2020). "Consistently, the tumor volumes were significantly larger in the anti-CCL21 and anti-CCR7 treatment groups than in the IgG control group." (PMID 32094452, 2020). "We found that the CCL21-DC tumor Ag vaccine in combination with PD-1 blockade therapy rescued TIL activity, causing enhanced tumor cytolysis." (PMID 32570793, 2020). "Pre-clinical studies have demonstrated that CCL19/CCL21 producing lymphatic endothelial cells can actively guide the chemotactic migration of CCR7-expressing tumor cells." (PMID 32340161, 2020). "Functional analysis demonstrated that CCL8 and CCL21 are involved in carcinogenesis, tumor immune escape mechanisms and chemoresistance in BC by several cancer-related kinases, miRNAs and transcription factors (ETS and E2F gene family)." (PMID 33146700, 2020).
tumor (continued). "Functional analysis demonstrated that CCL8 and CCL21 were involved in carcinogenesis, tumor immune escape and chemoresistance in BC." (PMID 33146700, 2020). "The chemokine receptor CCR7 is a key protein involved in the metastasis of tumor cells to sentinel lymph nodes where there is an abundance of its ligand CCL21." (PMID 32872485, 2020). "For patients who have reduced CD8 T cells in their tumors and/or low expression of tumor PD-L1, CCL21-DC tumor Ag vaccine will be of clinical benefit." (PMID 33167311, 2020). "Another study demonstrated that CCL21 secreted by tumor cells can establish an immune tolerant tumor microenvironment, thus promoting tumor progression." (PMID 33146700, 2020). "CCL21 functions as a pivotal regulator of cell proliferation, invasion, apoptosis and tumor metastasis." (PMID 33146700, 2020). "This indicates that hypoxia reduces CCL19/ELC and CCL21/SLC protein expression in a tumor but this effect is dependent on the tumor model." (PMID 32781743, 2020). "This approach utilizes an intratumoral administration of CCL21-DC that is limited by the geographical location of the tumor and the number of times the tumor can be injected." (PMID 32570793, 2020). "Accumulating in the tumor, CCL21-FA-UCNPs@mesoporous silica induced the migration of CCR7+ DCs and Jurkat T cells." (PMID 33240857, 2020). "The lymphatic vessels function as the sink for the interstitial flow; it has been postulated that interstitial flow and CCL21 act in conjunction to guide migrating tumor cells to lymphatics in the formation of metastases." (PMID 32340161, 2020). "Studies have shown that C-C chemokine receptor type 7 (CCR7), a G protein-coupled receptor, is the receptor of CCL21 and aberrantly expressed in certain tumor types." (PMID 33158173, 2020). "In this study, we are evaluating the generality of this observation by combining DC with tumor Ag and CCL21 to enhance T cell infiltration of tumors." (PMID 33167311, 2020). "Intratumoral delivery of CCL21 augmented the tumor-killing efficacy of adoptive cell therapy (ACT) in a murine model of melanoma by promoting T-cell survival rather than recruitment." (PMID 33381115, 2020). "The expression levels of CCL21 had a significant inverse correlation with tumor purity in 17 TCGA cancer types (cor ≤−0.3)." (PMID 32774369, 2020). "IHC of the tumor sections revealed an increase in CD3T cells, caspase 3 apoptotic tumor cells, and perforin and granzyme B expression in the anti-PD-1 plus CCL21-DC tumor lysate vaccine treatment group compared to diluent control and monotherapy." (PMID 32570793, 2020). "Flow cytometry analyses revealed increased frequency (4-fold) of activated CD8 T cells expressing granzyme B in the anti-PD-1 plus CCL21-DC tumor lysate vaccine treatment group in comparison to monotherapy." (PMID 32570793, 2020). "While this trial is ongoing in the right clinical setting, we are evaluating the systemic CCL21-DC tumor lysate vaccine." (PMID 32570793, 2020). "These immune cells have been shown to enhance tumor CCL21 expression, which facilitates tumor immune escape." (PMID 32153581, 2020). "In summary, the dual roles of the CCR7/CCL21 axis in protective immunity and tumor promotion suggest that their targeted therapies must be carefully evaluated." (PMID 32340161, 2020). "Recent studies in cancer immunotherapy have investigated the use of WT CCL21 as a chemoattractant of dendritic and T cells to the tumor." (PMID 32340161, 2020). "In this study, we combined dendritic cells (DCs) with tumor Ags and CCL21 to enhance T cell infiltration of tumors." (PMID 32570793, 2020). "These strategies have varied from use of the LTβR ligand LIGHT (TNFSF14) to adoptive transfer of DC expressing CCL21, and have shown efficacy in a number of diverse tumor models." (PMID 33013886, 2020). "Additional studies reported that the intra-tumoral injection of recombinant CCL21 significantly delayed tumor progression and stimulated cytotoxic immune responses." (PMID 32340161, 2020).